CD27 (CD27 molecule)
Diseases named in the same sentence as CD27 in open-access papers (continued):
Sharing a sentence is not in itself a finding about the gene and the disease.
dengue (5 papers, 2011 to 2020). "This study analyzed the rs8099917 of IFNL3, rs2267966 of CD27, and rs9277534 of HLA-DPB1 for their association with dengue severity in a Thai population." (PMID 33308178, 2020). "Future studies on other SNPs of CD27 are required because the plasma level of soluble CD27 was higher in severe dengue than in mild dengue." (PMID 33308178, 2020). "This is the first report of the genetic association of IFNL3, CD27, and HLA-DPB1 with dengue outcomes." (PMID 33308178, 2020). "In parallel, frequencies of CD27+CD38hiCD138+ plasma cells were higher in dengue patients than in febrile controls (median, 4.1 vs. 0.9%; P < 0.01) and in DHF/DSS patients compared to DF patients (median, 7.1 vs. 1.9%; P < 0.05)." (PMID 31736948, 2019). "Furthermore, significantly higher percentages of CD19+,CD20−,CD27+CD138+ plasma cells (p = 0.0036) were observed in dengue compared to control patients between days 4 and 7 after fever." (PMID 22216280, 2011). "In addition, CD19+CD27− naïve B cells isolated from dengue patients were refractory to TLR/anti-IgM stimulation in vitro, which correlated to the increased expression of inhibitory Fcγ receptors (FcγR) CD32 and LILRB1 on CD19+CD27− naïve B cells from DENV-infected patients." (PMID 31736948, 2019). "Four to seven days after onset of fever, secondary dengue patients possessed a significantly higher percentage of CD19+,CD20−,CD27+,CD138− plasmablasts (p = 0.0007) compared to control patients." (PMID 22216280, 2011). "To identify genes associated with dengue severity that have not been studied yet, we performed genetic association analyses of interferon lambda 3 (IFNL3), CD27, and human leukocyte antigen-DPB1 (HLA-DPB1) genes in Thai dengue patients." (PMID 33308178, 2020). "CD19+CD24hiCD38hi and CD19+CD27− naïve B cells from dengue patients did not produce IL-10 cytokine upon stimulation." (PMID 31736948, 2019). "The percentage of naïve cells (CD27−) was decreased within the CD19+ B cell compartment between DENV patients and DENV-negative febrile controls (median, 78.1 vs. 69.0%; P < 0.05) and in DHF/DSS patients compared to mild dengue (median, 59.3 vs. 72.0%; P < 0.05)." (PMID 31736948, 2019). "To obtain complete knowledge of genes/markers that predict dengue outcomes, we investigated genes that have not been studied to date, interferon lambda 3 (IFNL3), CD27, and human leukocyte antigen-DPB1 (HLA-DPB1)." (PMID 33308178, 2020).
depression (5 papers, 2021 to 2025). "CD8+ T cells, CD11b+ monocytic myeloid-derived suppressor cells, and CD27+ B cells are also correlated with depression, with CD27+ B cells specifically mediating the effects of the microbial methionine biosynthesis III pathway during disorders." (PMID 40804450, 2025). "Our final results were BMI, fatigue, depression, unstable emotions, and the proportion of CD27+CD28+ Th/Treg, CD27−CD28− Th/Treg, CD45RA−CD27− Th, and CD45RA+HLADR+ Th cells." (PMID 34955935, 2021). "BMI, fatigue, depression, unstable emotions, and CD27+CD28+ Th/Treg, CD27−CD28−Th/Treg, CD45RA−CD27− Th, and CD45RA+HLADR+ Th cells may be important characteristics of the differences." (PMID 34955935, 2021). "Furthermore, BMI, fatigue, depression, unstable emotions, CD27+CD28+ Th/Treg, CD27−CD28− Th/Treg, CD45RA−CD27− Th, and CD45RA+HLADR+ Th cells may be important characteristics between SLE patients with- and without-anxiety groups." (PMID 34955935, 2021).
lupus nephritis (5 papers, 2015 to 2025). Glomerulonephritis in the context of systemic lupus erythematosus. "These include expansion of circulating follicular helper T cells and CD21low IgD- CD27- age-associated or atypical memory B cells.The latter have been observed more frequently in patients with lupus nephritis." (PMID 40465409, 2025). "The proportion of CD27+IgD+ B cell in patients with lupus nephritis (n = 10, median 5.0% (range: 2.0–11.1)) was lower than those in SLE patients without renal involvement (n = 7, median 11.9% (range: 4.7–32.6)) (P = 0.032)." (PMID 26090500, 2015). "When naïve (live CD19+ CD27−) and memory (live CD19+ CD27+) B cells were gated, high levels of BAFF-secreting B cells were observed in the MN and lupus nephritis patients were observed compared with the healthy controls." (PMID 29423047, 2018). "Moreover, SLE patients with lupus nephritis had lower level of CD27+IgD+ B cells than SLE patients without renal involvement." (PMID 26090500, 2015).
nasopharyngeal carcinoma (5 papers, 2023 to 2025). A carcinoma arising from the nasopharyngeal epithelium. "CD70 on nasopharyngeal carcinoma cells binds to CD27 on naïve CD4+ T cells, driving differentiation to Tregs and their activation." (PMID 40270603, 2025). "Apart from hematological malignancies and NSCLC, CD27 expression was detected in tumor bearing mice (; RCC (and nasopharyngeal carcinoma among other cancers." (PMID 40205178, 2025). "Nasopharyngeal carcinoma cells promote the development and suppressive activity of Tregs through the interaction of CD70 and CD27." (PMID 40270603, 2025). "Signaling between CD70 and CD27 was identified as the only significant contact interaction between CD4+ naïve T cells, Tregs, and nasopharyngeal carcinoma (NPC) cells in the TME." (PMID 37828948, 2023).
non-Hodgkin lymphoma (5 papers, 2012 to 2025). Distinct from Hodgkin lymphoma both morphologically and biologically, non-Hodgkin lymphoma (NHL) is characterized by the absence of Reed-Sternberg cells, can occur at any age, and usually presents as a localized or generalized lymphadenopathy associated with fever and weight loss. "In HIV-positive individuals at risk for developing non-Hodgkin lymphoma (pre-NHL), CD8+PD-1+CD27+CXCR4− T-cells positively correlate with CD4+FoxP3+PD-1+ T-cells expressing CD27, CD28, ICOS, and CD71." (PMID 41148820, 2025). "Neoplastic lymphoid cells in non-Hodgkin lymphoma express CD27 and are considered responsible for the increased sCD27 production." (PMID 23145841, 2012). "In NK cells CD70, the ligand of the tumor necrosis factor receptor CD27, is highly expressed by non-Hodgkin lymphoma (NHL) cells." (PMID 34680190, 2021). "Co-expression of CD70 and CD27 can be found on the surface of malignant B cells in non-Hodgkin lymphomas (NHL) such as diffuse large B cell lymphoma (DLBCL), follicular lymphoma, follicle center lymphoma, mantle cell lymphoma, Burkitt lymphoma, and Waldenström macroglobulinemia." (PMID 34991665, 2022).
cervical cancer (4 papers, 2020 to 2024). A primary or metastatic malignant neoplasm involving the cervix. "TISIDB was employed to examine immune infiltration in cervical cancer, revealing that IDO1 levels exhibit a significantly positive association with ICOS, C10orf54, CD27, CD28, CD70, and other immunostimulatory factors, which negatively regulate the expression of CD276." (PMID 39312339, 2024). "High specificity and sensitivity of secreted CD40, CD27, and TIM-3 for cervical cancer make these proteins potential therapeutic targets for immunotherapy with radiation." (PMID 32802959, 2020). "Secondly, we identify CD40, CD27, and TIM-3 to specifically discriminate cervical cancer from other groups and CD40, CD28, and TLR2 to positively correlate to genital inflammation." (PMID 32802959, 2020). "Biomarker discovery analysis revealed that three immune checkpoint molecules, specifically CD40, CD27, and TIM-3, exhibit excellent or good discriminatory properties for cervical carcinoma compared to healthy controls and dysplasia." (PMID 32802959, 2020). "Combination therapies with monoclonal antibodies targeting CD40, CD27, or TIM-3 might be a potential approach to achieve better therapeutic outcomes in advanced and recurrent cervical cancer." (PMID 32802959, 2020).
chronic graft versus host disease (4 papers, 2020 to 2025). Chronic graft versus host disease (GVHD) is a complication that can occur after a stem cell or bone marrow transplant in which the newly transplanted donor cells attack the transplant recipient's body. "Contrary to this, another team investigating patients with chronic graft-versus-host disease (GVHD) demonstrated that treatment with MSCs led to an increase in the number of CD27 memory B cells and a decrease in plasma BAFF, associated with the increased expression of BAFF-R in peripheral B cells." (PMID 39684227, 2024). "Whereas patients after allogeneic HSCT have high numbers of CD19+IgD+CD27- naïve B cells, this B-cell subpopulation was significantly lower in individuals suffering from chronic graft-versus-host disease (cGvHD)." (PMID 34950155, 2021).
diabetes (4 papers, 2018 to 2024). "Studies using the Scottish Diabetes Research Type 1 Bioresource and the Finish Diabetic Nephropathy cohorts showed that biomarker panels that included KIM-1 and CD27 greatly improved accuracy." (PMID 33327377, 2020). "Statistical analysis of area 2, which comprised switched memory B cells with a CD21+CD24+CD27+CD38intCD95+IgD− phenotype, revealed that CXCR3 expression was reduced in individuals with long-standing diabetes relative to healthy donors in Study A (p < 0.05) and Study B (p < 0.005)." (PMID 29881878, 2018).
gastric cancer (4 papers, 2021 to 2025). A primary or metastatic malignant neoplasm involving the stomach. "Compared with normal human stomach epithelial cells, CD27 was highly expressed in three stomach cancer cells lines, AGS, MGC-803, and MKN-45." (PMID 38169519, 2024). "CD27/CD70 is expressed in CD20+ B cells and CD8+ T cells in the tumor microenvironment of gastric cancer." (PMID 33575321, 2021).
glioblastoma (4 papers, 2017 to 2024). The most malignant astrocytic tumor (WHO grade IV). "Directly comparing glioblastoma and RRMS patients, higher fractions of CD5+ activated TZB (Bc 11) and CD24+/CD27+ Bregs (Bc 19) were noted in the PB of RRMS patients." (PMID 39497174, 2024). "Regarding the Bc and Pc compartment, RRMS and glioblastoma patients shared an increase in CD19+CD20− DN Bc, CD21− DN memory Bc, and Pc as well as a reduction in activated TZB while CD24+/CD27+ Bregs were only reduced in glioblastoma patients compared to controls." (PMID 39497174, 2024). "Nevertheless, sorting of the endogenous CD27-positive CAR-T cell population yielded a CAR-T preparation that outperformed CD27-negative CAR-T cells in orthotopic glioblastoma xenografts." (PMID 35053463, 2022).
Granuloma (4 papers, 2015 to 2022). A compact, organized collection of mature mononuclear phagocytes, which may be but is not necessarily accompanied by accessory features such as necrosis. "In R2, there were no CD27+ lymphocytes within the abscess and there were a few within non-reactional granulomas." (PMID 26635870, 2015).
head and neck squamous cell carcinoma (4 papers, 2018 to 2024). A squamous cell carcinoma that arises from any of the following anatomic sites: lip and oral cavity, nasal cavity, paranasal sinuses, pharynx, larynx, and salivary glands. "This study aimed to construct a radiomics model that predicts the expression level of CD27 in patients with head and neck squamous cell carcinoma (HNSCC)." (PMID 36458007, 2022). "Anti-CD27 may also enhance the efficacy of other ADCP-dependent tumour-targeting mAbs in other cancers, such as anti-EGFR in head and neck squamous cell carcinoma and anti-GD2 in neuroblastoma." (PMID 30413184, 2018).
hepatocellular carcinoma (4 papers, 2019 to 2024). A malignant tumor that arises from hepatocytes. "It was suggested that the poor prognosis of the patients with hepatocellular carcinoma could be positively associated with CD11b-CD27-(DN) NK cells infiltrating with insufficient secretion of IFN-gamma secretion in the focal tissues." (PMID 32075046, 2020). "In contrast, in patients with hepatocellular carcinoma and high grade serous ovarian tumors, tumor-infiltrating B lymphocytes exhibited an atypical memory phenotype (CD27–IgD–)." (PMID 38702630, 2024).
pancreatic cancer (4 papers, 2019 to 2025). "For tumors which are immunologically “cold” due to a low tumor mutational burden such as pancreatic cancer, CD27 agonistic mAbs in combination with tumor-antigen loaded DC could be used to expand the T cell repertoire." (PMID 30788290, 2019). "In other studies, it was reported that cancer exosomes induce suppressor CD27- /CD28- CD8+ T-cells phenotype in head and neck cancer models and inhibit the antigen-presenting function of dendritic cells in pancreatic cancer cell line model." (PMID 39883638, 2025). "Although the role of CD19+CD24+CD38+ and CD19+CD24+CD27+ regulatory B cells have been investigated in patients with type 1 autoimmune pancreatitis, the specific mechanism of action of CD19 is yet to be determined in pancreatic cancer." (PMID 34737763, 2021).
parasite infection (4 papers, 2019 to 2024). "While memory T cells are less effective, CD27− TemL do reduce parasitemia, and are the most protective memory phenotype." (PMID 37205446, 2023). "Persistent parasite infection, including Leishmania major or P. chabaudi, generate recirculating Tcm that do not protect as well as activated Teff or Tem, defined as previously divided CD4+CD62Llo Tem/Teff, or distinguished as CD127− Teff and CD127hi CD44hi CD62Llo CD27− Tem." (PMID 37205446, 2023).
pneumonia (4 papers, 2019 to 2023). An acute, acute and chronic, or chronic inflammation focally or diffusely affecting the lung parenchyma, caused by an infection in one or both of the lungs (by bacteria, viruses, fungi, or mycoplasma.). "The results corroborated a difference only for CD27 and consisted in a steeper estimated increase before the time of pneumonia onset in controls than in cases." (PMID 38187375, 2023). "On that note, the increasing levels of CD27 in our polytrauma controls compared to cases until the time of pneumonia onset likely reflect continued activation of T cells and thus potentially, the need for their effective control to limit immune-mediated lung damage." (PMID 38187375, 2023). "Of subsets of CD3+ T cells, the frequencies of cluster 06 identified as NKT cell with markers of CD3+ CD3+CD56+CD8a+TCRab+CD45RA+CCR7−CD45RO+Tbet+GranzymeB+ and cluster 12 as CD4+ TCM with markers of CD3+CD4+TCRab+CD45RA−CCR7+CD45RO+CD27+CD127+ significantly decreased in acute pneumonia." (PMID 34841705, 2021). "The expression levels of CD27, CD28, CD59, OX40, CD40L, CD270, PD‐1, Tim3, EOME, HLA‐DR, TCRab and TIGIT were higher, while CD45, CD45RO and Tbet were lower in cluster 18 of patients with acute pneumonia." (PMID 34841705, 2021).
thyroid cancer (4 papers, 2021 to 2025). "Statistical analysis of the LFC profiles with the BRAF V600E-specific inhibitor dabrafenib differentiated BRAF V600E and non-BRAF V600E thyroid cancers, with six peptides (BAD_93- 105, CD27_212-224, MPIP1_172-184, PRKDC_2618-2630, and RB_242-254) showing p < 0.05." (PMID 37760447, 2023).
allergic rhinitis (3 papers, 2022 to 2024). Inflammation of the nasal mucous membranes caused by an IgE-mediated response to external allergens. "When we divided the patients with allergic rhinitis or allergic asthma and with chronic sinusitis, only patients with allergic manifestations showed a significantly higher percentage of IgD+IgM− CD27+ B cells." (PMID 38392874, 2024). "In addition, some surface molecules have been validated to promote allergic rhinitis flare-ups, such as CD19 on IgD- CD27- B cell, CD25 on IgD+ CD38- B cell." (PMID 39399526, 2024).
Behçet's disease (3 papers, 2017 to 2022). "Furthermore, it has been recently demonstrated that patients with Behçet's disease have significantly lower memory B cell numbers in peripheral blood, particularly CD27+IgA+ B cells, when compared to controls, but treatment with adalimumab restored to normal levels blood B cell numbers." (PMID 28886017, 2017).
bronchiectasis (3 papers, 2022 to 2025). Segmental, irreversible dilation of the bronchial tree resulting in the accumulation of secretions which leads to obstruction. "Recurrent URTI and LRTI, bronchiectasis, Addison’s disease, dysgammaglobulinemia, ↓CD19+ B cells, inverted CD4/CD8 ratio, ↑CD8+CD45RA+CD27- TEMRA cells, abnormal CD4+CD45RA/RO ratio." (PMID 41583441, 2025).
Burkitt lymphoma (3 papers, 2005 to 2024). A rare form of malignant mature B-cell non-Hodgkin lymphoma. "Although the in vitro ADCC activity of CDX-527 was less potent than the 2B3 mAb, AVEx2B3 and 2B3 both similarly improved the survival of immunodeficient mice transplanted with the human Burkitt’s lymphoma line Raji that has high CD27 expression." (PMID 32451681, 2020). "Additionally, BMP-6 induced cell death in CD27+ memory B cells as well as in a Burkitt lymphoma cell line (Ramos)." (PMID 15877825, 2005).
chronic myeloid leukemia (3 papers, 2022 to 2024). "Indeed, CD27 expression enables immune escape, as high expressions of sCD27 are linked to a poor prognosis for AML, and abnormal CD27 expression can be found on LSCs of AML and chronic myeloid leukemia." (PMID 37894427, 2023).
colon adenocarcinoma (3 papers, 2021 to 2022). "We found that the efficacy of depleting mAb such as anti-CTLA-4 and anti-CD25 can be enhanced by CD27 mAb in a murine colon adenocarcinoma tumour model." (PMID 35288635, 2022). "Agonistic CD27 monoclonal antibodies can be used to enhance the efficacy of depleting antibodies such as anti-CTLA-4 in a colon adenocarcinoma tumour model." (PMID 35288635, 2022). "Study identified autophagy-related lncRNAs CD27.AS1 to constructed a prognostic signature in colon adenocarcinoma." (PMID 33517850, 2021).
coronary artery disease (3 papers, 2022 to 2025). "Additionally, the discovery of proteins NRP1 and CD27 offers new insights into the pathophysiology of coronary heart disease (CHD) in patients with type 2 diabetes." (PMID 40362167, 2025). "Using 18 surface antibodies to subtype B cells obtained from women with coronary artery diseases, B cells were subtyped into 7 clusters with 3 clusters of CD27+ B cells and 4 clusters of CD27− B cells." (PMID 36045343, 2022).
endometrial cancer (3 papers, 2023 to 2024). Primary or metastatic malignant neoplasm involving the endometrium (mucous membrane that lines the endometrial cavity). "The CD27 showed strong diagnostic value in 4 cancers and marked a positive prognosis for CESC, intracervical adenocarcinoma, HNSC, and endometrial cancer, and a poor prognosis for UVM." (PMID 38169519, 2024).
esophageal cancer (3 papers, 2016 to 2024). A primary or metastatic malignant neoplasm involving the esophagus. "Similarly, our findings suggest that CD27 on CD20-CD38- B cells can inhibit the development of esophageal cancer." (PMID 38601154, 2024). "CD27 on CD20- CD38- B cell, as a potential mediator, reduced the intensity of Smoking status: Never in preventing or inhibiting esophageal cancer (mediating effect: -4.12%)." (PMID 38601154, 2024). "In particular, it was observed that in the case of the preventive effect of Smoking status: Never on esophageal cancer, the absolute count of CD62L plasmacytoid dendritic cells mediated a reduction of 4.21%, while the mediating effect of CD27 in CD20-CD38-B cells was -4.12%." (PMID 38601154, 2024).
glaucoma (3 papers, 2013 to 2025). Increased pressure in the eyeball due to obstruction of the outflow of aqueous humor. "In the retina of glaucoma patients, CD27/CD3 immunostaining was consistently negative and we only found CD27+/IgG+ cells." (PMID 23451242, 2013). "Interestingly, CD27+ cells (indicative of memory B cells or plasma cells) are consistently observed in the retinas of glaucoma patients but not in the retinas of controls." (PMID 41146424, 2025). "In glaucoma patients, the absence of CD27+/CD3+ T cells is notable, while the presence of CD27+/IgG+ plasma cells suggests a potential role for these cells in late‐stage disease progression." (PMID 41146424, 2025).